ALB (albumin)
Diseases named in the same sentence as ALB in open-access papers (continued):
Sharing a sentence is not in itself a finding about the gene and the disease.
heart failure (continued). "For this reason, several nutritional assessment tools in hospitalized patients with heart failure had incorporated serum albumin in their patient evaluation." (PMID 32867269, 2020). "It has the advantage of considering only four variables, namely, age, urgent intervention, albumin, and heart failure." (PMID 32545670, 2020). "Lower serum creatinine, higher serum albumin, and urea reduction rates predicted heart failure events." (PMID 33584644, 2020). "Following forward selection, MPV (p = 0.033), Urea (p = 0.007), Albumin (p < 0.001), age (p < 0.001), type of admission (p = 0.018), heart failure (p < 0.001) and CKD (p = 0.013) were retained for model development." (PMID 30764796, 2019). "Albumin levels are affected by both the diet and several common diseases, such as liver failure, heart failure, kidney damage or enteropathy." (PMID 30822279, 2019). "The predictive value of albumin level was confirmed in various diseases, including patients with heart failure and autoimmune diseases, such as Kawasaki disease and GBS12–15." (PMID 29343812, 2018). "It has the great advantage of considering only four variables, all of which can be assessed preoperatively (age, urgency of the intervention, albumin, and heart failure)." (PMID 29378647, 2018). "Older age, low albumin, assistance with daily activities, nursing home history, comorbidities of cancer and heart failure; and hospitalizations prior to initiating dialysis were the 7 significant predictors of mortality." (PMID 29703177, 2018). "A global approach in the management of these patients is needed, especially focusing on women and patients with frailty, low albumin levels, and ischemic aetiology heart failure." (PMID 27577747, 2016). "This study provided the first data regarding the following independent risk factors associated with the occurrence of pleural effusion: older age; male gender; the presence of heart failure; and lower albumin." (PMID 27287396, 2016). "Previous studies reported that an elevated level of AST and a lower level of serum albumin occur in patients with severe cardiac complications, such as acute myocardial infarction or heart failure." (PMID 26741992, 2016). "Screening should focus specially on patients with low albumin levels, frailty, or heart failure of ischemic aetiology, and women in particular." (PMID 27577747, 2016). "Compared with HD patients, PD patients had more cardiovascular disease, less heart failure, higher levels of serum potassium, hemoglobin, serum albumin, serum pre-albumin, and lower levels of brain natriuretic peptide." (PMID 27824950, 2016). "This study provided the first data regarding the following four independent risk factors associated with the occurrence of pleural effusion: older age; male gender; the presence of heart failure; and lower albumin." (PMID 27287396, 2016). "Compared with HD patients, PD patients had more cardiovascular disease, less heart failure, higher levels of serum potassium, hemoglobin, serum albumin, and serum pre-albumin, and lower levels of brain natriuretic peptide." (PMID 27824950, 2016). "In this study, older age, male gender, the presence of heart failure and lower albumin were found by multivariate analysis to be independently predictive variables for the occurrence of pleural effusion in scrub typhus." (PMID 27287396, 2016). "Serum albumin is one of the biochemical tests to assess nutritional status in heart failure used in numerous studies." (PMID 26471898, 2015). "Previous studies have reported that RDW correlated negatively with markers of nutrition, such as albumin, prealbumin, transferrin, and total cholesterol levels, in heart failure patients and in PD patients." (PMID 25961836, 2015). "Control-1s had greater body weights, less CAD, heart failure, catheter use (compared to graft/fistula), missed treatments, and greater eKt/V, albumin, hemoglobin, phosphorus, calcium, potassium, creatinine, and nPCR compared to CPA cases." (PMID 25530881, 2014).
heart failure (continued). "Conditions such as hepatic dysfunction and heart failure can reduce the elimination of theophylline; and low albumin states reduces the amount of protein-bound drug in the blood, then in these situations, aminophylline should be used with caution." (PMID 25674137, 2014). "Furthermore, the authors examined the relationship between the quantity of human albumin infused within 24 hours and in-hospital mortality rates in both the overall Heart Failure (HF) cohort and the subgroup with HF plus albumin ≤ 2.9 g/dL." (PMID 40279952, 2025). "A recent study indicated that the FAR might serve as a more effective prognostic indicator than albumin or fibrinogen alone in cases of heart failure." (PMID 41030320, 2025). "Overall, the mechanisms of albumin reduction in heart failure patients are multifaceted." (PMID 40104144, 2025). "Therefore, the authors suggest that future studies should have a prospective design in order to better understand the efficacy and safety of human serum albumin in patients with heart failure." (PMID 40279952, 2025). "The relationship between albumin levels and volume status may partly explain its predictive value for heart failure." (PMID 41458488, 2025). "Furthermore, the risks of heart failure and pulmonary edema were higher in the albumin group than in the control group." (PMID 40649163, 2025). "Previous studies have shown that the GNRI may be superior to albumin levels in the prognostication of patients with cancer and heart failure, but both indices may be superior in those with AMI." (PMID 39269471, 2025). "Another parameter, albumin, is documented to impact the incidence and prognosis of heart failure." (PMID 40429565, 2025). "The results identified the following independent risk factors for VTE: length of hospital stay, age ≥70 years, Caprini score ≥3, respiratory or heart failure, body mass index (BMI) ≥30 kg/m2, high platelet count, low serum albumin level, and elevated D-dimer level." (PMID 41244769, 2025). "In the absence of albumin, 1 μM of empagliflozin attenuated late INa in mouse cardiomyocytes with heart failure or sodium-channel mutations." (PMID 39717441, 2024). "Low levels of serum albumin are capable of aggravating circulatory congestion and enhancing oxidative stress, inflammatory response as well as infection sensitivity, thereby worsening heart failure patients’ prognosis." (PMID 38418846, 2024). "Patients with heart failure often havea chronic inflammatory response that may lead to impaired liver function,resulting in reduced albumin synthesis." (PMID 39742221, 2024). "Other important predictors of a higher MACE risk after PCI were non-radial access, heart failure and higher Killip class, albumin, CONUT score, ACE inhibitors, and GRACE score." (PMID 38609875, 2024). "Additionally, the Neutrophil to Serum Albumin Ratio (NPAR), NLR, and ALB have been reported to correlate with mortality in heart failure patients." (PMID 39726875, 2024). "Low erythropoietin production and decreased serum albumin may be related to the mechanism by which RDW affects the prognoses of heart failure patients." (PMID 37206106, 2023). "Increased mortality risks were also associated with specific infectious causes (like pneumonia, necrotizing fasciitis, and endocarditis), as well as certain comorbidities (notably heart failure and malignancy) and laboratory test results (such as albumin, creatinine, and hemoglobin levels)." (PMID 37959230, 2023). "The higher levels of urinary albumin before TAVI were reported to be associated with not only AKI onset but also all-cause death and heart failure readmission and may be noticed for predicting the prognosis after TAVI26." (PMID 37903844, 2023). "Whether there is a multiplicative interaction of lactate/albumin (L/A) ratio and geriatric nutritional risk index (GNRI) on the mortality of critically ill elderly patients with heart failure (HF) remains unclear." (PMID 37226575, 2023).
heart failure (continued). "In univariate cox regression analysis, age, male sex, smoking, heart failure, previous myocardial infarction, peripheral vascular disease, higher proteinuria, lower eGFR, lower serum albumin and 1SD increase in all inflammatory biomarkers were associated with all-cause mortality." (PMID 35042473, 2022). "Therefore, low albumin is the sum of many harmful factors in patients with heart failure, which is expected to provide important prognostic information for patients with heart failure." (PMID 36171266, 2022). "We used a generalized additive model to determine the nonlinear correlation between serum albumin and 14th day, 28th day and 90th day all-cause mortality in patients with heart failure." (PMID 36171266, 2022). "In patients with heart failure complicated with ARDS, the predictive effect of albumin on all-cause mortality is greatly reduced, and the reason may be related to the close relationship among infection, low albumin and ARDS." (PMID 36171266, 2022). "Third, wherever GDF-15/Albumin ratio is associated with cardiovascular disease or heart failure is not fully studied." (PMID 35204349, 2022). "Clinical studies have identified increased urinary albumin excretion among heart failure patients." (PMID 32681438, 2021). "A mediation analysis using data from the CANVAS Program also found that markers of plasma volume, in addition to serum urate and urine albumin‐to‐creatinine ratio, had the largest mediation effects in canagliflozin versus placebo and reduction of heart failure." (PMID 34277971, 2021). "In addition, sex, serum CRP level, albumin level, neutrophil count, PNI score, NSCLC stage, application of platinum, NLR, metastasis, surgery, heart failure, KPS score, and miR-1231 levels were associated with overall mortality." (PMID 32939184, 2020). "In addition, gender, serum CRP level, albumin level, neutrophil count, PNI score, NSCLC staging, platinum application, NLR, metastasis, surgery, heart failure, and KPS score were also associated with overall mortality." (PMID 32939184, 2020). "In recent years, it has been suggested that adding albumin to lactulose could be more useful than lactulose alone for hepatic encephalopathy, which might also be beneficial for patients with heart failure." (PMID 32012742, 2020). "Low serum albumin level is commonly found in patients with heart failure, both HFpEF and HFrEF." (PMID 32867269, 2020). "Previous studies have indicated that advanced age, elevated baseline heart rate, increased serum expressions of glucose, albumin and creatinine are all independent predictors of incident heart failure in elderly patients, which is in accordance with our results." (PMID 30045695, 2018). "The equation included nine readily available clinical variables (age, sex, race, eGFR, urine albumin-to-creatinine ratio, smoking, diabetes mellitus, and history of heart failure and stroke), and it was externally validated in a large cohort of elderly CKD patients." (PMID 29317867, 2017). "Accounting for clinical parameters including heart failure, comorbidity index, and serum albumin/electrolyte levels, scores assessed by the Edmonton frailty scale showed significantly negative association with QRS duration (β coefficient = − 0.29, t = − 2.03, p = 0.048)." (PMID 26528415, 2015). "age, sex, race/ethnicity, ALT, AST, GGT, cholesterol, calcium, ALB, P, glycohemoglobin, platelet, vitamin D intake, calcium intake, smoking status, family history of osteoporosis, cancer, chronic obstructive pulmonary disease, heart failure, and use of glucocorticoid." (PMID 41601928, 2026). "Moreover, low ALB levels can promote pulmonary edema and fluid retention, leading to heart failure." (PMID 40371078, 2025). "Furthermore, albumin, being a colloid, increases fluid volume, which could potentially exacerbate symptoms of heart failure." (PMID 40279952, 2025). "ALB may be a core target of ZWD in the treatment of heart failure." (PMID 41403091, 2025).
heart failure (continued). "Therefore, integrating albumin and creatinine into sACR may more comprehensively reflect the pathophysiological changes of heart failure and have enhanced prognostic value." (PMID 39027002, 2024). "Given the complex interplay between heart failure, systemic inflammation, and renal dysfunction, integrating serum albumin and creatinine into sACR may offer a more comprehensive assessment of the pathophysiological alterations in heart failure, thus enhancing prognostic accuracy." (PMID 39027002, 2024). "A study involving 5795 elderly individuals, tracked over a period of 9.6 years, confirms that the incidence of new onset heart failure was significantly associated with low serum albumin concentration, independent of risk factors, body mass index, and inflammation." (PMID 38580915, 2024). "The onset and progression of heart failure are characterized by the activation of neurohormones, inflammatory responses, metabolic dysregulation, and other factors, leading to abnormal levels of biomarkers such as serum albumin and creatinine, especially during acute exacerbations." (PMID 39027002, 2024). "However, in decompensated heart failure, serum albumin levels may decrease due to increased extracellular fluid volume." (PMID 37791200, 2023). "Therefore, albumin reduction in patients with initial heart failure may be largely influenced by other factors such as inflammation." (PMID 36171266, 2022). "Although albumin replacement therapy has been widely used clinically for patients with heart failure, its role in improving the prognosis remains unknown, and the effects of exogenous albumin supplementation on the mortality of patients with heart failure have not been demonstrated." (PMID 35931952, 2022). "In addition, several studies have shown that the nutritional index PNI, GNRI and COUNT for the long-term prognosis of elderly patients with heart failure are significantly better than plasma albumin levels, total lymphocyte statistics, body mass index (BMI) and others." (PMID 34710169, 2021). "In the worsening renal function group, there were higher occurrence rate of heart failure and severe coronary artery stenosis, lower rate of percutaneous coronary intervention, lower medication rate of renin-angiotensin blocker, lower plasma albumin, magnesium and hemoglobulin level." (PMID 34606471, 2021). "Studies have suggested that albumin levels are negatively correlated with the incidence of AMI, and in patients with acute coronary syndrome (ACS), low albumin levels were found to be independent predictors of all-cause mortality and the deterioration of heart failure during hospitalization." (PMID 32355581, 2020). "Finally, the association could, in part, be influenced by clinical factors such as higher heart rate, obesity, low albumin, heart failure, and CHD." (PMID 29117224, 2017). "Studies examining the role of albumin-corrected anion gap (ACAG), an emerging promising prognostic biomarker for critical illnesses, in predicting mortality of ICU patients with heart failure (HF) are limited." (PMID 40951817, 2025). "Previous studies already revealed that lactate/albumin ratio (LAR) is related to adverse outcomes in acute myocardial infarction, acute pancreatitis, and heart failure." (PMID 40538408, 2025). "Significant differences between the groups were found for: Smoking, Heart failure, CKD, NPAF, BNP, Creatinine, eGFR, Albumin, FBG, RDW-CV, Neutrophils, Lymphocyte, LAD, LVEDD, LVEF, APPLE score, SII, NLR and PLR." (PMID 40860368, 2025). "Patients who developed AKI were older and had more frequent metastatic disease, heart failure, and gastrointestinal primaries, higher CCI and APACHE II scores, lower haemoglobin and serum albumin levels, and higher BUN (all P < 0.05)." (PMID 41281063, 2025). "Our study constructed a nomogram for predicting the risk of VTE based on age, BMI, Caprini scale score, respiratory/heart failure, length of hospital stay, PLT, serum albumin, and D-dimer levels." (PMID 41244769, 2025).
heart failure (continued). "In addition, BMI and serum albumin levels may fluctuate due to the existence of heart failure." (PMID 38004141, 2023). "Recent study showed that the fibrosis-5 index (FIB5), which was calculated by albumin, alkaline phosphatase, aspartate transaminase, alanine aminotransferase and platelet count, had better prognostic value than FIB4 in patients with heart failure." (PMID 37087702, 2023). "Cox regression analysis was performed for age, sex, BMI, albumin, CCI ≥5, presence of cancer, COPD, dementia, DM, peptic ulcer, heart failure, home discharge, time to readmission, dependent condition, and white nails." (PMID 35602847, 2022). "Serum levels of ALB and GLB can be used in combination to predict the survival of patients with heart failure." (PMID 34917645, 2021). "Several recent studies have found that serum albumin/globulin ratio (AGR) can predict the prognosis of various diseases, including cancers, chronic kidney disease, heart failure, and peritoneal dialysis." (PMID 34917645, 2021). "We aimed to investigate the clinical significance of albumin-bilirubin (ALBI) score, an assessment tool of liver function, on outcomes in heart failure (HF) patients treated with CRT." (PMID 34830658, 2021). "Three variables showed a similar directional association with each mode of death but a stronger relationship with one mode over the other: longer duration of HF (PFD), serum albumin (PFD) and chloride (PFD), all indicators of more advanced heart failure." (PMID 34101002, 2021). "Multivariate analysis showed that miR-1231, surgery, platinum application, albumin level, KPS score, and heart failure as independent prognostic factors predicted OS." (PMID 32939184, 2020). "Specifically, cases and control-2s were similar in terms of weight, CAD, heart failure, treatment time, shortening of treatment time, ESA dosing, number of missed treatments, eKt/V, albumin, phosphorus, calcium, bicarbonate, and nPCR." (PMID 25530881, 2014). "Given that albumin levels can be modified by inflammation and hydration, future studies should include analysis of inflammatory markers (e.g., CRP) to better understand the interaction between nutritional status and the course of heart failure." (PMID 40077630, 2025). "These patients remained at high risk of admission to MICU after multivariable adjustment for SOFA score, PaO2/FiO2 ratio, CKD, heart failure, chronic liver disease, WBC, Hgb, ALB, D-dimer, AST, and C-reactive protein (CRP) (SMAT4: OR 4.731, 95% CI 1.853–12.075; SMIT4: OR 6.449, 95% CI 2.422–17.170)." (PMID 41211659, 2025). "Additionally, the prevalence of heart failure, cerebrovascular disease, and pulmonary hypertension was higher, while BMI, Hb, RBC, L, ALB, UA, TC, and LDL-C levels, as well as the prevalence of malignancy, were lower in the Q4 group (all p < 0.05)." (PMID 40969798, 2025). "Investigations on heart failure in adults have demonstrated that it does not change by age, body mass index (BMI), creatinine, hemoglobin, and albumin levels, in contrast to NT pro BNP." (PMID 38929297, 2024). "More and more studies have revealed that there is a significant negative correlation between serum albumin levels and cardiovascular diseases, especially coronary atherosclerotic heart disease, heart failure and atrial fibrillation." (PMID 38655495, 2024). "When determining pseudoexudates, a serum-pleural effusion albumin gradient (SPAG) of >1.2 g/dL and a serum-pleural effusion protein gradient (SPPG) of >3.1 g/dL together showed a sensitivity of 100% in heart failure and a sensitivity of 99% in hepatic hydrothorax." (PMID 39416574, 2024). "It was discovered that individuals with heart failure have a negative acute-phase reactant (pre-albumin) and RDW relation that is very significant." (PMID 39807412, 2024).